DENND4A (DENN domain containing 4A)
Description:
Probable guanine nucleotide exchange factor (GEF) which may activate RAB10. Promotes the exchange of GDP to GTP, converting inactive GDP-bound Rab proteins into their active GTP-bound form. According to PubMed:8056341, it may bind to ISRE-like element (interferon-stimulated response element) of MYC P2 promoter.
Synonyms: IRLB; MYCPBP
Tractability: PROTAC: ubiquitination databases record sites on it; its protein half-life has been measured.
Gene: Protein-coding gene on chromosome 15 (65,658,046 to 65,792,293, reverse strand). Ensembl gene ENSG00000174485.
Subcellular location: Nucleus
Subcellular location (Human Protein Atlas): Nucleoli rim; Mitotic chromosome; Nucleoplasm
Pathways (Reactome):
Vesicle-mediated transport: RAB GEFs exchange GTP for GDP on RABs
Gene Ontology:
Molecular function: guanyl-nucleotide exchange factor activity; protein binding; DNA binding
Biological process: regulation of DNA-templated transcription; regulation of Rab protein signal transduction
Cellular component: cytosol; nucleus
Genetic constraint (gnomAD): Loss-of-function variants: 54 observed, 153 expected, observed/expected ratio (o/e) 0.35, 90% interval 0.28 to 0.44. The upper end of that interval is the gene's LOEUF score, 0.44, which puts it in group 1 of 6, group 1 being the genes least tolerant of losing a copy. Missense variants: 1,546 observed, 2,038.7 expected, observed/expected ratio (o/e) 0.76, 90% interval 0.73 to 0.79. Synonymous variants: 626 observed, 701.61 expected, observed/expected ratio (o/e) 0.89, 90% interval 0.83 to 0.95.
Homologues: Orthologues: chimpanzee DENND4A (99% identical), macaque DENND4A (99% identical), dog DENND4A (95% identical), pig DENND4A (94% identical), guinea pig DENND4A (93% identical), rabbit DENND4A (93% identical), rat Dennd4a (90% identical), mouse Dennd4a (90% identical), tropical clawed frog dennd4a (71% identical). Paralogues in human: DENND4C (49% identical), DENND4B (36% identical), DENND3 (12% identical).
Diseases named in the same sentence as DENND4A in open-access papers:
DENND4A is named in the same sentence as 7 diseases in open-access papers, as found by Europe PMC text mining. Sharing a sentence is not in itself a finding about the gene and the disease. The quoted sentences say what the papers report.
hearing loss (1 paper, 2012). "Moreover, three different subtypes of Usher syndrome, an inherited condition characterized by hearing loss and progressive vision loss, have been mapped to the vicinity of the DENND4A locus at 15q22.31." (PMID 23226104, 2012).
Parkinson disease (1 paper, 2019). A progressive degenerative disorder of the central nervous system characterized by loss of dopamine producing neurons in the substantia nigra and the presence of Lewy bodies in the substantia nigra and locus coeruleus. "Moreover, both CAMTA1 and DENND4A were independently found to be ‘Master Regulators’ (MRs) of neurodegenerative disease transcriptional programs in an in vivo Parkinson’s disease model and a cultured motor neuron-based ALS model." (PMID 30357366, 2019).
cancer (3 papers, 2018 to 2025). A tumor composed of atypical neoplastic, often pleomorphic cells that invade other tissues. "Among these upregulated genes, Dennd4a, Nfil3, Hspa1b, Chac1, Ddit4, Mex3b, Lysmd3, and Zbtb10 are mainly involved in oxidative stress and inflammation response, whereas Plcxd2, Dusp1, Cep85l, and Dusp8 are generally considered as tumor‐suppressor genes by inhibiting proliferation of cancer cells." (PMID 40231790, 2025). "We highlight that there are not studies in cancer for FDX1, MULT, VAMP4 and DENND4A genes or its protein products." (PMID 33265245, 2018).
neurodegenerative disease (1 paper, 2019). A disorder of the central nervous system characterized by gradual and progressive loss of neural tissue and neurologic function. "This suggests a central role for both CAMTA1 and DENND4A proteins in driving transcriptional programs underlying neurodegenerative diseases." (PMID 30357366, 2019). "Interestingly, CAMTA1 and DENND4A both have strong links to neurodegenerative disease." (PMID 30357366, 2019). "Unlike CAMTA1 and DENND4a, no direct connection between MIG12 and neurodegenerative disease has previously been described." (PMID 30357366, 2019).
DENND4A also shares sentences with these, for which no sentence is quoted: tumor (2 papers); melanoma (1); Usher syndrome (1).